TSLP (thymic stromal lymphopoietin)
Diseases named in the same sentence as TSLP in open-access papers (continued):
Sharing a sentence is not in itself a finding about the gene and the disease.
psoriasis (continued). "Anti‐TSLP treatment ameliorated psoriasis‐like plaque formation, ear thickness, and trans‐epidermal water loss (TEWL) in both mouse models, significantly in DKO* mice but not in DKO*K15 mice." (PMID 31556482, 2019). "We also observed that VEGFα expression, a pro‐inflammatory mediator in psoriasis, decreased with anti‐TSLP treatment." (PMID 31556482, 2019). "Local administration of anti‐TSLP in psoriasis‐like mice resulted in the reduction of the phenotype due to epidermal hyperplasia regression and inhibition of STAT‐5 phosphorylation (p‐STAT5) in the epidermis." (PMID 31556482, 2019). "Blocking TSLP in psoriasis‐like mice reduced skin inflammation and decreased epidermal proliferation, VEGFα expression, and STAT5 activation." (PMID 31556482, 2019). "Although TSLP was established as major proallergic cytokine in atopic dermatitis (AD), recently it has been also proved to contribute to human psoriasis physiopathology." (PMID 29316717, 2018). "Emerging evidence indicates that TSLP is also involved in chronic inflammatory (i.e., chronic obstructive pulmonary disease and celiac disease) and autoimmune (e.g., psoriasis, rheumatoid arthritis) disorders and several cancers." (PMID 30057581, 2018). "Several studies have examined the role of TSLP in the context of psoriasis." (PMID 38666958, 2024). "The serum level of both TSLP and IL-31 is elevated in patients with pruritic psoriasis, as well the number of IL-31-immunoreactive mast cells at lesional sites, while TSLP expression is increased in the epidermis of psoriatic lesions." (PMID 35321329, 2022). "Serum TSLP is also statistically increased and correlated with the severity of this disorder, suggesting its role as a prospective disease activity biomarker in psoriasis patients." (PMID 34249003, 2021). "More importantly, inhibition of the TSLP/TSLPR pathway could be beneficial for psoriasis patients and warrants additional clinical investigations." (PMID 34249003, 2021). "Importantly, during psoriasis‐like disease initiation, TSLP is produced by mutant HF‐SCs and at late stage also by non‐mutant HF‐SCs." (PMID 31556482, 2019). "Interestingly, while the expression of TSLP remained increased in mutantGFP bulge HF‐SCs and mutantGFP b‐KCs at the mid‐term of the psoriasis‐like development, its expression was reduced at the latest stage (D30)." (PMID 31556482, 2019). "Thus, given the central role of mDC-derived IL-23 in psoriasis, and its relevance in driving IL-17 production, TSLP is becoming a novel player within the complex cytokine network supporting the IL-23/IL-17 axis." (PMID 29316717, 2018). "In addition to chemokines, we found that TWEAK activity was required in vivo for the production of two other mediators of atopic dermatitits or psoriasis, TSLP and IL-19, respectively." (PMID 28530223, 2017). "TWEAK alone cannot promote full AD or psoriasis phenotypes but it can promote chemokines common to both AD and psoriasis from keratinocytes and fibroblasts, as well as characteristic cytokines of both diseases such as TSLP and IL-19." (PMID 28530223, 2017). "This phenomenon could be explained by the dominance of Th1 response in patients with psoriasis and the unresponsiveness of their immune cells to TSLP." (PMID 19557146, 2009). "Also, the level of TSLP was higher in patients with psoriasis with psoriatic arthritis and smokers." (PMID 38666958, 2024). "Besides, the significant mitigation of imiquimod induced psoriasis by anti-human TSLP antibodies TAVO101 and tezepelumab also validated the substantial contribution of a functional human TSLP-TSLPR signaling cascade in the establishment of IMQ induced psoriasis in the transgenic mice." (PMID 39726595, 2024). "TSLP may be a potential indicator for early detection and diagnosis of active psoriasis." (PMID 37546687, 2023).
psoriasis (continued). "Since elevated expression levels of TSLP in the epidermis and increased TSLP serum levels have been reported in patients with psoriasis, this cytokine appears to be partially involved not only in the pathogenesis of psoriasis, but also in the induction of itch in psoriasis." (PMID 33182442, 2020). "In addition, further investigations will be required to determine whether local neutralization of TSLP in combination with specific HF‐SCs pro‐inflammatory mediators such as PGE2 could be an effective treatment for psoriasis." (PMID 31556482, 2019). "Our data suggest that the elevated of level of TSLP released from keratinocytes due to BRAP deficiency might mediate the crosstalk between the epidermal cells and immune cells and thereby contributing to the altered pathological changes observed in psoriasis - like skin lesion in knockout mice." (PMID 38169666, 2024). "For instance, several pro‐inflammatory cytokines and arachidonic acid metabolic pathways described to be critical in psoriasis, such as IL‐23, IL‐1α, TNF‐α, TSLP, or PTGS2, were up‐regulated." (PMID 31556482, 2019). "Taken together, our investigation demonstrated the novel mechanism wherein the alarmins IL-33 and TSLP exacerbate NET formation that may drive enhanced inflammation and oxidative stress in psoriasis." (PMID 41596128, 2026). "Sidler reported that fibroblasts can respond to the effects of tumor necrosis factor-like weak inducer of apoptosis (TWEAK) by expressing IL-19, which induces the expression of thymic stromal lymphopoietin (TSLP) and regulates many chemokines to affect the development of psoriasis and AD." (PMID 39420283, 2024). "In addition, TAVO101 showed a trend of slightly more efficacious than tezepelumab in inhibiting TSLP-driven proliferation of activated CD4+ T cells in an ex vivo study and in an in vivo study with imiquimod induced psoriasis mouse model." (PMID 39726595, 2024). "In imiquimod induced psoriasis mouse model, the induction of human TSLP expression in the skin lesions upon IMQ application confirmed the equivalent temporal and spatial pathophysiological expression of human TSLP transgene as its murine counterpart." (PMID 39726595, 2024). "In addition, the other ligand for CD127, thymic stromal lymphopoietin (TSLP), has been found statistically increase in psoriasis patients and correlated with severity of psoriasis." (PMID 38590608, 2024). "In contrast, an increased expression of TSLP in non‐mutantTom bulge HF‐SCs was observed at D30, while non‐mutantTom b‐KCs did not express TSLP at any stage of psoriasis‐like development." (PMID 31556482, 2019). "Furthermore, TSLP was increased in sera of both psoriasis‐like mouse models, DKO* and DKO*K15, at day 30 after psoriasis‐like induction." (PMID 31556482, 2019). "While Th2 cytokines such as IL-4, IL-13, IL-33, and TSLP dominated the inflammatory landscape in AD and bullous pemphigoid, Th1 and Th17 immune responses, primarily mediated by IFN-γ and IL-17, characterized psoriasis, lichen planus, and specific forms of GvHD." (PMID 41479908, 2025). "Interestingly, bulge HF‐SCs labeled with CD200 did not express TSLP in psoriasis patients, neither lesional nor non‐lesional scalp, while sub‐bulge ORS increased its expression in lesional HFs." (PMID 31556482, 2019). "To determine the TSLP autocrine/paracrine regulation in co‐cultures of mutantGFP with non‐mutantTom KCs, we purified by FACS GFP+ and Tomato+ KCs after TSLP neutralization and analyzed gene expression of pro‐inflammatory mediators in psoriasis‐like disease (Fig EV5D–M)." (PMID 31556482, 2019). "Thus, although the current literature would suggest a more prevalent role for IL-7 thanks to its Th1- and Th17- promoting activity, a potential contribution of TSLP to psoriasis-like skin cannot be ruled out at present." (PMID 31406267, 2019).
psoriasis (continued). "Autocrine regulation by TSLP secretion may activate pro‐inflammatory mediators, such as NF‐κB, IL‐1β, and G‐SCF in mutant bulge HF‐SCs and mutant basal keratinocytes, pushing the inflammatory signaling toward psoriasis progression." (PMID 31556482, 2019). "Our finding that TWEAK can promote the expression of both TSLP and IL-19 from keratinocytes or dermal fibroblasts provides a further mechanism by which TWEAK can contribute to the development and/or maintenance of the clinical phenotypes of both AD and psoriasis." (PMID 28530223, 2017). "The epithelium-derived cytokines, namely TSLP, IL-25 and IL-33 represent a new target for future therapies, especially in terms of itch control and, possibly, side-effects minimization, but not enough studies, especially in psoriasis, have been conducted in this direction." (PMID 34944487, 2021). "Even though the role of TSLP in psoriasis is not completely resolved, TSLP has been reported to induce DC maturation and to drive to a DC-derived IL-23 production leading to the hypothesis that it could have a comparable role in other IL-23-driven autoimmune diseases." (PMID 32849527, 2020). "Calcipotriol application results in the production of thymic stromal lymphopoietin (TSLP), a potent inducer of Th2 responses, in keratinocytes of psoriasis lesions but not normal skin." (PMID 39744952, 2025).
helminth infection (35 papers, 2013 to 2025). "An important role for TSLP in resistance to helminth infection was shown by infection of mice with T. muris, in which TSLP blockade made resistant mice susceptible and TSLP receptor deficient mice have enhanced worm burdens." (PMID 25028340, 2014). "Several studies linked TSLP to lung inflammation and helminth infection, although the role of TSLP in airway inflammation using clinically relevant protease allergens HDM and papain have not been yet addressed." (PMID 23738146, 2013). "The alarmins IL-33, IL-25 and TSLP are mainly secreted by stromal and epithelial cells in tissues and were linked to chronic inflammatory diseases, such as allergic lung inflammation, or to resistance against worm infections." (PMID 37063913, 2023). "Tuft cells are chemosensory epithelial cells that produce IL-25 and thymic stromal lymphopoietin (TSLP), which induce a Th2 immune response to prevent helminth infection." (PMID 39339792, 2024). "Following helminth infection of the small intestine, stromal cells in adjacent adipose tissue start producing interleukin-33 (IL-33) and thymic stromal lymphopoietin (TSLP)." (PMID 39107476, 2024). "Upon helminth infection, various types of alarmin cytokines, including IL-25, IL-33, and thymic stromal lymphopoietin (TSLP) were secreted from intestinal epithelial cells." (PMID 37635188, 2023). "Among them, ILC2s (group 2 ILC) can produce type 2 cytokines in response to alarmin cytokines such as IL-33, IL-25, and TSLP (Thymic Stromal Lymphopoietin), and so play an important role in allergic illnesses, anti-helminth infection, and metabolic balance." (PMID 36611440, 2023). "Thymic stromal lymphopoietin (TSLP) induced by helminth infection, supports basophil proliferation and promotes induction of Th2 cytokine responses in Trichinella infection." (PMID 33335529, 2020). "Pulmonary exposure to instigators of type 2 immunity and inflammation, such as helminth infection and allergen exposure, induce the production of IL-33, IL-25, and thymic stromal lymphopoietin (TSLP) from lung epithelial and endothelial cells." (PMID 32625201, 2020). "Ultimately, mice with ineffective mast cells are unable to prime an effective type 2 immune response regulated by IL-33, IL-25 and TSLP in response to helminth infection and are unable to clear the parasites." (PMID 32363166, 2020). "They respond to epithelial cell-derived alarmins IL-25, IL-33, and thymic stromal lymphopoietin (TSLP), which in turn launch Th2 responses to expel helminth infection and involved in allergic airway inflammation." (PMID 32051038, 2020). "In response to helminth infection, innate immune cells and intestinal epithelial cells secrete Th2 cytokines including IL-4, IL-5, IL-9, IL-13, IL-25, IL-33 and thymic stromal lymphopoietin (TSLP)." (PMID 30670631, 2019). "In this specific niche, adventitial stromal cells promote ILC2 homeostasis in steady-state and in response to helminth infection through the production of IL-33 and thymic stromal lymphopoietin (TSLP)." (PMID 31507605, 2019). "This correlation between reductions in these epithelial derived cytokines and the delayed Th2 response seen experimentally is further evidence in support of the Th2 polarizing effect of IL-25, IL-33 and TSLP in certain helminthic infections." (PMID 30670631, 2019). "Various factors have been reported to regulate TSLP expression under different pathological conditions, among which miR-375 was shown to up-regulate TSLP in intestinal epithelial cells following helminth infection." (PMID 26919238, 2016). "In terms of helminth infection, TSLP has been shown to play a major role in protective immunity to T. muris." (PMID 24942690, 2014). "Mast cells are required for the production of IL-25, IL-33, and TSLP by intestinal epithelial cells following helminth infection and during subsequent anti-helminth responses." (PMID 23653627, 2013).
helminth infection (continued). "During helminth infection, intestinal epithelial cells induce the production of IL-25, IL-33, and TSLP." (PMID 23653627, 2013). "It was later shown that innate lymphoid cells could respond to the tissue alarmin TSLP to produce IL-5 and IL-13, but this appears to occur mainly in the skin leaving the impact of TSLP in other stages of helminth infection less clear." (PMID 32793230, 2020). "Direct helminth-induced damage to and death of lung epithelial cells can be one of the initial triggering events in helminth infection, leading to release of epithelial derived alarmins IL-25, IL-33, thymic stromal lymphopoietin (TSLP), and chemokines CXCL1, CXCL2, CXCL8, and eotaxins." (PMID 33193446, 2020). "In helminth infection and migration through mucosal surfaces such as the gastrointestinal tract, lungs, or skin, the tissue damage that ensues serves as an initiating stimulus, and the epithelial cells release alarmins, crucial cytokines such as IL-25, IL-33, and thymic stromal lymphopoietin (TSLP)." (PMID 40869321, 2025). "Analogous to their Th2 counterparts, ILC2s play a key role in controlling helminth infection, while perpetuating allergen‐induced allergic inflammation via the production of IL‐5 and IL‐13 in response to alarmins IL‐33, IL‐25, and thymic stromal lymphopoietin (TSLP)." (PMID 36331092, 2023). "Interleukins 33, 25, and thymic stromal lymphopoietin (TSLP) are core components of type two immune responses and have been studied extensively using helminth infection models." (PMID 40944312, 2025). "Damaged IECs release cytokines such as IL-33, IL-25, and thymic stromal lymphopoietin (TSLP), playing a crucial role in worm infections." (PMID 38203591, 2023). "The type 2 cytokines IL-5 and IL-13 are also secreted early during a helminth infection by innate lymphocytes (ILC2) in response to the release of IL-33 and TSLP from mucosal epithelial sensor cells." (PMID 34083746, 2021). "ILC2 express GATA binding protein-3 (Gata3), produce IL-13 and IL-5 in response to IL-25, IL-33, and thymic stromal lymphopoietin (TSLP) and contribute to the defense against helminthic infections as well as to the pathogenesis of allergic inflammation [1248]." (PMID 34910301, 2021). "Upon stimulation with IL-25, IL-33, or thymic stromal lymphopoietin (TSLP), ILC2 can produce IL-5, IL-13, and IL-4, similar to Th2 cells, which contribute to the control of helminth infection and pathology of allergic inflammation." (PMID 29354125, 2017). "These cells are stimulated by thymic stromal lymphopoietin (TSLP), IL-25, and IL-33 and after helminth infection produce effector cytokines, such as IL-4 and IL-13, and provide an important source of Th2-type cytokines." (PMID 27648452, 2016). "In the small intestine, epithelial tuft cells remained TSLP reporter-negative throughout a kinetic analysis of acute Nippostrongylus brasiliensis helminth infection." (PMID 41225178, 2025). "While more sub‐cellular examination of IL‐25's activity is ongoing, IL‐33 and TSLP research has been hampered by a lack of clarity regarding their functional sources during helminth infections." (PMID 40944312, 2025). "Inhibition of mast cell function in vivo has also been linked to an overall reduction in IL-33, as well as IL-25 and TSLP both in the context of helminth infection as well as without." (PMID 32363166, 2020). "Similarly, proximal large intestine epithelial cells remained TSLP reporter-negative after Trichuris muris helminth infection, which is known to require TSLP12." (PMID 41225178, 2025). "During the early phases of helminth infection, alarmin signals such as interleukin (IL)-25, IL-33, and thymic stromal lymphopoietin (TSLP) are released by non-hematopoietic cells in response to tissue damage and act to induce rapid proliferation and expansion of group 2 innate lymphoid cells (ILC2)." (PMID 40181967, 2025).
helminth infection (continued). "The cytokines, IL-25, IL-33, and thymic stromal lymphopoietin (TSLP) assume key roles here and in mice, precursors of lineage negative (ILC2) that can respond to IL-25/33 and helminth infection are found in many tissues around the body 61,68." (PMID 24942690, 2014).